AFP (alpha fetoprotein)
Diseases named in the same sentence as AFP in open-access papers (continued):
Sharing a sentence is not in itself a finding about the gene and the disease.
yolk sac tumor (continued). "Serum AFP in the normal range for age reliably excludes a yolk sac tumor and for this reasons some authors reported that this fact indicates that a testis sparing procedure is feasible." (PMID 23217189, 2012). "Elevated serum levels of AFP in patients with immature teratoma may be explained by immature liver and gastrointestinal components and not primarily by foci of yolk sac tumor." (PMID 41118662, 2026). "Serum levels of alpha‐fetoprotein (AFP) may be elevated both in pure immature teratomas and in immature teratomas with foci of yolk sac tumor, even in those with microscopic foci (≤ 3 mm) of yolk sac tumor (Heifetz lesions)." (PMID 41118662, 2026). "This patient was identified as having undifferentiated cancer with a small amount of yolk sac differentiation, indicating that a negative AFP result on immunohistochemistry cannot completely exclude the possibility of yolk sac tumor components, possibly due to their limited presence in the tumor." (PMID 38966065, 2024). "For the diagnosis of yolk sac tumors, however, the overall sensitivity of AFP staining is not high." (PMID 37138865, 2023). "AFP was often elevated in GCTs without a yolk sac tumor component, especially immature teratoma." (PMID 36995447, 2023). "AFP is a strong marker for the non-seminomatous GCC entity yolk-sac tumor." (PMID 27283990, 2016). "AFP, which is positive in yolk sac tumor, is negative as well in GSTs." (PMID 23762714, 2013). "The immunohistochemical profile was similar in the original metastasis and the two orthotopic tumors, and was characteristic of a yolk sac tumor with extensive expression of cytokeratine Cam5.2, but with only focal expression of EMA and patchy immunoreactivity for AFP." (PMID 23937707, 2013). "Another explanation for raised serum levels of AFP in patients with immature teratoma without histologically documented yolk sac tumor elements could be sampling error because immature teratomas are usually large and therefore small areas of yolk sac tumor may be missed." (PMID 41118662, 2026). "Glypican hepatoid yolk sac tumor is morphologically and immunohistochemically very similar to HAC, and both can express SALL4, Glypican-3, and AFP, and often do not express somatic cell markers such as CK7 and EMA." (PMID 40740864, 2025). "Instead, LHCGR levels were significantly higher in patients with elevated AFP, which indicates that LHCGR in non-seminoma either originates or is related to the yolk sac tumor component." (PMID 32466562, 2020). "AFP was positive in all yolk sac tumor and most embryonal carcinomas, whereas OCT3/4 was often expressed in embryonal carcinomas but absent in yolk sac tumors." (PMID 32064359, 2020). "A robust immunohistochemical panel in which yolk sac tumors would be positive for CAM5.2, SALL4, AFP, and glypican-3 while negative for OCT3/4, CKIT, and, in general, CD30 is helpful on cell block preparations, as is the correlation with elevated serum AFP levels." (PMID 37510144, 2023).
chronic hepatitis (125 papers, 2004 to 2026). An active inflammatory process affecting the liver for more than six months. "The role of biomarkers was considered in this staging system; an elevated serum AFP level is believed to indicate hepatic regeneration in response to liver injury, and previous studies have shown an association between elevated AFP levels and advanced fibrosis in chronic hepatitis." (PMID 25133493, 2014). "Serum AFP levels also correlate significantly with histological inflammatory activity and the degree of hepatic fibrosis, particularly in chronic hepatitis." (PMID 41293148, 2025). "Randomized controlled trials have shown that screening HBV carriers and patients with chronic hepatitis with AFP and ultrasound twice a year can reduce HCC-related mortality." (PMID 39650722, 2024). "AFP can also be elevated in chronic hepatitis, liver cirrhosis and other diseases, which can easily lead to false positive results when used for tumor screening." (PMID 39650722, 2024). "In resource-rich countries, with the advent of surveillance with ultrasound scans and AFP in patients with chronic hepatitis, the clinical manifestation of patients has changed significantly." (PMID 37730538, 2023). "Apart from etiology, one possible reason for this discrepancy is that among patients with advanced fibrosis and chronic hepatitis, the serum AFP level can be elevated, so the sensitivity and specificity of AFP are limited." (PMID 36836479, 2023). "Clinically, an ultrasound, combined with AFP in serum, is used to monitor early HCC, but AFP is also elevated in embryonic-derived tumors, acute and chronic hepatitis, and other diseases." (PMID 36826102, 2023). "For example, one chronic hepatitis patient, P14, had the MethylHBV5k at 69.5%, the methylation level of region 5 at 72.4%, and an abnormal AFP level (141.9 ng/ml)." (PMID 32741373, 2020). "HCCR-1 expression is high in HCC, moderate in LC, and at basal levels in normal control and chronic hepatitis, with higher detection accuracy (78.2%) than AFP (64.6%) for discrimination between HCC and LC." (PMID 32923383, 2020). "Tomimaru and co-workers demonstrated that a combination of AFP and miR-21 improved accuracy of detection of chronic hepatitis and HCC." (PMID 31973032, 2020). "If they are the recipients with chronic hepatitis, periodic ultrasound and alpha fetoprotein monitering every 6-12 months are recommended among chronic hepatitis carriers because early detection of tumor can have a higher chance of receiving treatment." (PMID 28978168, 2017). "A recent study reported that in chronic hepatitis patients with AFP<20 ng/ml, DCP showed a high specificity of 100% in patients who combined with HCC, using a microchip capillary electrophoresis and liquid-phase binding assay." (PMID 27070780, 2016). "It was accepted that the elevated AFP resulted from primary chronic hepatitis instead of a malignant hepatic lesion." (PMID 24059753, 2013). "Here we present a case of a non-typical hepatic pseudolesion observed on CT that was complicated by chronic hepatitis and elevated AFP." (PMID 24059753, 2013). "CTNNB stands out as a promising marker for HCC, as well as for HCC with low AFP, since it shows at least 3 fold abundance over patients with chronic hepatitis." (PMID 19578489, 2008). "Similarly, another study of participants with HBV or a history of chronic hepatitis (n = 18,816) in Shanghai found that, despite a low adherence of 58.2%, biannual screening with AFP and ultrasound reduced HCC mortality by 37%41." (PMID 39578653, 2024). "Circulating levels of LINC00152, XLOC014172, and RP11-160H22.5 were able to distinguish HCC patients from cirrhotics, chronic hepatis, and healthy subjects, with very high accuracy when combined with AFP (AUC of 0.986 for HCC vs. chronic hepatitis and 0.985 for HCC vs. healthy controls)." (PMID 34068786, 2021).
chronic hepatitis (continued). "Also, the cirrhotic patient group showed significantly elevated AFP levels when compared with control (p ˂ 0.001) and chronic hepatitis groups (p = 0.010)." (PMID 34452571, 2021). "For the chronic hepatitis B group, the median value of the serum AFP level was 2.1 ng/mL, 3.2 ng/mL, 6.6 ng/mL, and 42.7 ng/mL in the chronic hepatitis group with a normal ALT level, 1 upper limit of normal (ULN) < ALT level ≤ 2 ULN, 2 ULN < ALT level ≤ 5 ULN, and ALT level > 5 ULN, respectively." (PMID 33490235, 2020). "Multivariate logistic regression on factors for HCC showed that, in comparison with chronic hepatitis, in addition to gender (OR 19.288, P = 0.003), age (OR 1.137, P < 0.001) and AFP (OR 1.001, P = 0.014), PTX3 (OR 1.639, P < 0.001) was an independent risk factor for HCC." (PMID 33219288, 2020). "Subjects at highest risk for HCC are those with chronic hepatitis and advanced fibrosis; hepatic inflammation can result in elevation of AFP and up to 30% of HCC was non-AFP producing." (PMID 32741373, 2020). "However, AFP levels below 100 ng/mL are less specific since slightly elevated AFP can also be observed in patients with chronic hepatitis." (PMID 31635078, 2019). "Circulating miR-21 was also higher in HCC than chronic hepatitis patients and healthy controls; furthermore, its levels correlated with miR-21 expressed in HCC tumor tissue and it had better diagnostic sensitivity than alpha fetoprotein (AFP)." (PMID 29282036, 2017). "Chronic hepatitis and abnormal AFP further complicated the case." (PMID 24059753, 2013). "While there is poor diagnostic ability of serum AFP to detect HCC, serial increase of AFP value clinically may be helpful as a complementary method in chronic hepatitis patients under surveillance for HCC." (PMID 24369506, 2013). "Additionally, when comparing 16 HCC patients with low AFP (AFP < 20 ng/ml) to 15 patients with chronic hepatitis, CTNNB remains significantly elevated in the group of HCC patients with AFP < 20 ng/ml (median = 1307 pg/ml) (p = 0.036)." (PMID 19578489, 2008). "Firstly, our new method is necessary to compare with the best current biomarker AFP, and serum AFP levels are usually elevated in the patients with chronic hepatitis hospitalized at our hospital due to active or severe disease, which may therefore lead to bias in this comparison." (PMID 35747812, 2022). "However, the final pathological results revealed that the elevated AFP was caused by primary non-viral (B, C, or G) chronic hepatitis instead of the hepatic lesion." (PMID 24059753, 2013). "Further analyses indicated that AFP and PIVKA-II markers and combined models have good-to-excellent performance detecting curative resected HCC, separating HCC from chronic hepatitis, dysplastic, and hyperplasia nodules." (PMID 37932802, 2023). "AFP was significantly elevated in the HCC group compared with the control (p ˂ 0.001), chronic hepatitis (p ˂ 0.001), and cirrhotic patient groups (p = 0.034)." (PMID 34452571, 2021). "More recently, Shen and colleagues established an online calculator based on serum biomarkers including age, sex, AFP and PIVKA-II, to detect HCC in patients with chronic hepatitis." (PMID 33297335, 2020). "In a recent study, three circulating lncRNAs, namely LINC00152, RP11-160H22.5, and XLOC014172, combined with AFP, were able to distinguish HCC from chronic hepatitis patients or healthy controls with an AUC of 0.986 and 0.985, respectively." (PMID 32443747, 2020). "Nonspecific serum AFP increase occurs in from 15% to 58% of patients with chronic hepatitis and from 11% to 47% of cirrhotic cases." (PMID 40870535, 2025). "Moreover, AFP levels are normal in 40% of HCC patients, while also being elevated in patients with chronic hepatitis, LC, and other cancers." (PMID 37209815, 2023). "More knowledge on primary non-viral (B, C, or G) chronic hepatitis with greatly elevated AFP levels and Child A liver function is in need." (PMID 24059753, 2013).
chronic hepatitis (continued). "Here we present a case of hepatic pseudolesion observed by CT that was complicated by primary non-viral chronic hepatitis (B, C, or G) with elevated AFP." (PMID 24059753, 2013). "On the other hand, it is well known that AFP levels may increase in some patients with acute and chronic hepatitis without HCC and that elevation of AFP levels correlates with inflammation caused by background diseases and hepatocyte regeneration." (PMID 22697061, 2012). "However, AFP has important limitations: 30–40% of HCCs do not elevate AFP, false positives may occur in acute and chronic hepatitis from different etiologies, and its optimal threshold has not been established." (PMID 34069569, 2021). "The specificity of AFP is low and it can be elevated in pregnant women, acute and chronic hepatitis, gonadal tumors, and gastrointestinal tumors; in addition, approximately 40% of patients with HCC are non-secretors of AFP." (PMID 34660300, 2021). "Serum exo-miR-215-5p showed improved efficiency over serum AFP; however, it failed to distinguish between early-stage HCC and chronic hepatitis or LC." (PMID 31968558, 2020). "However, some patients with advanced HCC do not secrete AFP, moreover AFP can be elevated in conditions other than HCC, such as chronic hepatitis." (PMID 36081568, 2022). "Meanwhile, AFP, the most commonly used biomarker in HCC, is not specific for HCC and elevated levels of AFP may be seen in both patients with HCC and chronic hepatitis without cancer." (PMID 33219288, 2020). "Elevated serum AFP (e.g. levels > 20 ng/ml) is not a specific marker for HCC, since it is detected in a wide variety of non-hepatic malignancies and benign conditions, including acute and chronic hepatitis." (PMID 19578489, 2008). "However, it is well known that AFP may increase in some patients with acute and chronic hepatitis without HCC, and that the elevation of AFP correlates with inflammation of background disease and hepatocyte regeneration." (PMID 25970775, 2015).
diabetes (109 papers, 2005 to 2026). "c-IGF1R high was associated with AFP positivity (p = 0.037) and the diagnosis of diabetes mellitus (p = 0.034)." (PMID 39775131, 2025). "Those with consensus as risk factors for post-SVR HCC include diabetes mellitus, advanced age, high alpha-fetoprotein (AFP) level, and advanced liver fibrosis." (PMID 40624408, 2025). "The presence of PNS in HCC strongly correlates with tumor size and AFP levels, with diabetes potentially serving as a risk factor." (PMID 38674198, 2024). "Multivariate analysis revealed a strong correlation between PNS and levels of alpha-fetoprotein and tumor size, with diabetes also showing a significant statistical association (p < 0.05)." (PMID 38674198, 2024). "In the multivariate analysis, hypoglycemia was strongly associated with high AFP values (p < 0.0001) and also with diabetes, even if the latter only had statistical significance (p < 0.038)." (PMID 38674198, 2024). "Various independent factors were associated with NAFLD, including type 2 diabetes mellitus, elevated low-density lipoprotein levels, high hemoglobin levels, low platelet counts, and normal alpha-fetoprotein levels." (PMID 39200880, 2024). "Combinations of serum LOXL2 levels with serum AFP level, platelet count, age, and presence of diabetes mellitus, were identified as independent risk factors for post-SVR HCC development." (PMID 38740815, 2024). "Several studies have shown that old age, male sex, progression of fibrosis, diabetes mellitus, and elevated AFP levels are significant risk factors." (PMID 39720368, 2024). "The univariate Cox regression analysis revealed that age ≥75 years, M2BPGi ≥ 4.23, AFP ≥ 7.7 ng/mL, Ang2 ≥ 464 pg/mL, and diabetes were significantly associated with HCC occurrence after successful HCV eradication by DAAs." (PMID 36680221, 2023). "The univariate Cox regression analysis showed that age ≥75 years, FIB-4 index ≥ 3.67, M2BPGi ≥ 1.89, AFP ≥ 4.6 ng/mL, Ang2 ≥ 402 pg/mL, and diabetes were significantly associated with HCC occurrence after successful HCV eradication by DAAs." (PMID 36680221, 2023). "Despite the lack of specific predictors of HCC, several host factors, including liver fibrosis stage, older age, elevated AFP levels, and comorbidities such as diabetes and steatosis, have been associated with HCC occurrence." (PMID 34242330, 2021). "The clinical pattern of alcohol-related liver disease shows frequent association with diabetes and overweight/obesity, multi-nodularity and low production of AFP." (PMID 33232278, 2020). "In the Cox model, ALBI grade, tumor burden, alpha-fetoprotein, vascular invasion, diabetes mellitus and performance status were independent predictors linked with overall survival." (PMID 29555927, 2018). "For stillbirth, research to identify better predictors of placental dysfunction such as erythropoietin, pregnancy associated plasma protein A, alpha fetoprotein and angiogenic/antiangiogenic factors in women with diabetes is needed." (PMID 28597075, 2017). "However, little information is available about the potential association between melatonin and hepatic alpha-fetoprotein expression in diabetes." (PMID 37655263, 2023). "Compared to non-Hispanic Caucasians, AA patients at presentation were older, were more likely to have modifiable metabolic risk factor such as diabetes, had larger HCCs, had higher AFP values, were more likely to have gallstones, and were more likely to not meet Milan criteria." (PMID 35366282, 2021). "Several risk-predictive host factors, e.g., advanced liver fibrosis, older age, accompanying metabolic diseases such as diabetes, persisting hepatic inflammation, and elevated alpha-fetoprotein, as well as viral factors, e.g., core protein variants and genotype 3, have been reported." (PMID 28288626, 2017). "Comorbidities such as diabetes were identified in 89 patients (25.57%), while 112 patients (32.18%) had AFP levels >20 ng/mL, a tumor marker for HCC." (PMID 40662001, 2025).